IL31 (interleukin 31)
Diseases named in the same sentence as IL31 in open-access papers (continued):
Sharing a sentence is not in itself a finding about the gene and the disease.
atopic dermatitis (continued). "IL‐31 was measured in archived samples (31 serum and 31 CSF samples) of 40 dogs with SRMA, with atopic dermatitis and of healthy control dogs using a competitive canine IL‐31 ELISA." (PMID 39969014, 2025). "IL-31, as a neuroimmune modulator, also induces a distinct transcriptional programme in sensory neurons that leads to nerve fibre proliferation, which may explain why patients with atopic dermatitis exhibit increased sensitivity to minimal stimuli that provoke persistent itch." (PMID 41002407, 2025). "Here, we investigated the effect of histamine in an atopic dermatitis skin milieu sustained by TH2 cytokines (IL-4, IL-13 and IL-31), using human keratinocytes and full-thickness skin models with a developed epidermal layer." (PMID 36615633, 2023). "Another potential pruritogenic mechanism involves IL-31-mediated B-type natriuretic peptide (BNP) synthesis, a molecule which has been shown to induce atopic dermatitis skin inflammation." (PMID 36613861, 2022). "IL-31 has been shown to upregulate TRPA1 transcription and expression in itchy lesional skin in atopic dermatitis." (PMID 36613861, 2022). "In a study of atopic dermatitis, AD-MSCs exosomes significantly reduced mRNA expression of various inflammatory cytokines such as interleukin (IL)-4, IL-23, IL-31, and tumor necrosis factor-α (TNF-α) in atopic dermatitis skin lesions of the mouse model." (PMID 32483483, 2020). "The study found that IL-31 induced CCL1, CCL17, and CCL22 chemokines in atopic dermatitis-irritated skin." (PMID 30987029, 2019). "Earlier studies have shown involvement of IL-31 and its receptor components IL-31RA and OSMR in atopic dermatitis, pruritus and Th2-weighted inflammation." (PMID 26449657, 2015). "Inflammatory mediators such as the Th2 cell–derived cytokines IL-4 and IL-31 and TNF-α have been shown to impair epidermal differentiation and have been suggested to play important roles in the pathogenesis of atopic dermatitis." (PMID 23157658, 2013). "IFN-γ and IL-13 concentrations were lower in treated dogs than in healthy dogs and untreated dogs, whereas IL-31 concentrations were higher in dogs with atopic dermatitis than in healthy dogs, regardless of treatment status." (PMID 42071951, 2026). "By contrast, atopic dermatitis and Th2-related genes, including Il4, Il5, Il13 and Il31 were lowly expressed or not detected at all, and other atopic dermatitis-related transcripts (Ccr4, Ccl17, Ccl24) were not significantly differentially expressed." (PMID 38528069, 2024). "A two-part phase 1 single-dose trial was conducted between 2012 and 2015 to assess the efficacy of an anti-human IL-31 antibody (BMS-981164) produced by Bristol-Myers Squibb for atopic dermatitis, but the results were never published." (PMID 37509136, 2023). "The role of allergen sensitization in IL-31 production by T cells and specifically in the clinical context of atopic dermatitis (AD) has not been characterized." (PMID 36993985, 2023). "Not surprisingly, IL‐31 levels are elevated in pruritic diseases such as atopic dermatitis, prurigo nodularis, lichen planus, and uremic pruritus." (PMID 37632245, 2023). "The roles of IL-4, IL-13, IL-31, and TSLP in the pathogenesis of atopic dermatitis might involve a dysfunctional epidermal barrier and allergen sensitization, which are characterized by intense itching and pruritus." (PMID 37676892, 2023). "The highest mean IL-31 content was measured in samples from patients with SRMA (n = 18), followed by the second highest mean IL-31 level in serum samples from the dogs with atopic dermatitis (n = 3) and patients with MUO (n = 15)." (PMID 37627467, 2023). "Increased IL-31 expression was found in lesional and nonlesional skin of patients with atopic dermatitis." (PMID 33924978, 2021).
atopic dermatitis (continued). "Therefore, the objective of this study was to investigate the effect/mechanism of the action of apigenin in modulating IL-31 release in human mast cells (HMC-1) and in compound 48/80-induced itch in atopic dermatitis." (PMID 30987029, 2019). "IL-31 is a proinflammatory cytokine mediating multiple immune functions, whose involvement in a wide range of diseases, such as atopic dermatitis, inflammatory bowel diseases and cutaneous lymphomas, is now emerging." (PMID 26449657, 2015). "Blood IL-31 has been correlated to disease severity in atopic dermatitis but had not been studied in KD to date." (PMID 25122210, 2014). "IL-31 was measured in archived samples (49 serum and 52 CSF samples) of dogs with SRMA, meningoencephalitis of unknown origin (MUO), infectious meningoencephalitis, and atopic dermatitis, and of healthy control dogs using a competitive canine IL-31 ELISA." (PMID 37627467, 2023). "However, the ability of apigenin to modulate the newly discovered IL-31 cytokine responsible for itch in atopic dermatitis has not been investigated." (PMID 30987029, 2019). "In atopic dermatitis, IL-31 induces chemotaxis, Ca2+ mobilization, release of reactive oxygen species, surface expression of adhesion molecules and CCL26 in eosinophils, which in turn release IL-31, contributing to the maintenance of the inflammatory infiltrate." (PMID 29156718, 2017). "Some previous studies suggested that interleukin 31 (IL-31) and its receptor components IL-31RA and OSMR could be a key cytokine pathway involved in itching which accompanies a number of inflammatory skin conditions, mostly atopic dermatitis." (PMID 23970959, 2013). "Based on our findings it may be inferred that dogs with atopic dermatitis manifest skin lesions along with the inflammatory response, and the skin barrier proteins (Filaggrin and Involucrin) and inflammatory cytokines (TNF-α, IL-31, IL-13) seem to be key players in the pathogenesis of AD in dogs." (PMID 34075152, 2021). "IL-31 was shown to be upregulated in patients with atopic dermatitis, but it has not yet been clarified whether it is the allergen or a secondary factor that induces the expression of this cytokine; literature results showed that IL-31 activation could occur directly by allergen stimulation." (PMID 29713240, 2018). "In addition, the available data exhibited that IL-31 contributed to atopic dermatitis, nonatopic eczema, systemic lupus erythematosus (SLE), asthma, inflammatory bowel disease (IBD), familial primary cutaneous amyloidosis, Kawasaki disease, hepatitis B virus liver failure, and allergic rhinitis." (PMID 28572699, 2017). "IL-31 mRNA was reported to be overexpressed in pruritic atopic dermatitis but not in psoriasis which is a mainly TH1-dependent inflammatory disease, confirming an involvement of IL-31 in TH2-mediated skin diseases." (PMID 22853438, 2012). "However, it is crucial to emphasize that no significant changes were observed in classic factors of atopic dermatitis, such as TSLP and pro-inflammatory cytokines (TNF-α, COX-2, IL-6, IL-31, etc.), in our study." (PMID 38834629, 2024). "Within the study, interleukin-31 levels were measured in serum and cerebrospinal fluid samples of dogs affected by SRMA in comparison to dogs with atopic dermatitis (positive control), healthy dogs (negative control) and dogs with immune-mediated or infectious meningoencephalitis." (PMID 37627467, 2023).
dermatitis (40 papers, 2012 to 2025). An inflammatory process affecting the skin. "Due to its role in allergic inflammation, IL31 has earned the moniker the “itchy” cytokine and has been linked to inflammatory bowel disease, airway hypersensitivity in asthma, dermatitis, and pulmonary fibrosis." (PMID 38932146, 2024). "IL-31, often called an itchy or pruritogenic cytokine, is implicated in itch development in various skin disorders." (PMID 35893400, 2022). "IL-31 has been associated with sensory neuronal outgrowth, activation of ion channels that transmit pruritic signals, and impaired keratinocyte differentiation that amplifies skin inflammation and itch." (PMID 38397136, 2024). "However, it should also be noted that some other drugs, including epidermal growth factor receptor tyrosine kinase (EGFR-TK) inhibitors, may activate the IL-31/IL-33 axis as their adverse effect and initiate dermatitis, presumably by damaging keratinocytes and causing the release of IL-33." (PMID 41155460, 2025). "The studies on human skin and mice models have shown the over-expression of IL-31 and its receptor, IL-31RA, in dermatitis models." (PMID 38500882, 2024). "Mite infestation and IL-31 administration triggered itchy skin, increased LLS counts and DRG neuronal IL-31RA expression, and eventually caused dermatitis." (PMID 36674561, 2023). "Reduction in scratching frequency, dermatitis severity and trans-epidermal water loss (TEWL), decreased IL-6, IL-31 and IgEs serum levels." (PMID 37509136, 2023). "Of note, the inhibition of MAGL restored the anti-inflammatory effect THCV exerted on CREB, further supporting the IL-31 data on the importance of endogenous 2-AG levels in skin inflammation." (PMID 36769042, 2023). "Here, our results also show the ability of MAGL inhibition to counteract the anti-inflammatory action of THCV on IL-31 levels; thus, the resulting increased level of 2-AG can play a key role in skin inflammation." (PMID 36769042, 2023). "It is evident that our findings, along with other pertinent research, lay the groundwork for a deeper understanding of IL-31’s involvement in pruritic skin disorders, particularly CSU." (PMID 37762898, 2023). "IL-31 is a novel cytokine that has a proven role in the pathogenesis of skin inflammation, airway hypersensitivity and in a range of pruritic diseases." (PMID 35324695, 2022). "Continuous or repeated injection of IL-31 also evokes sustained scratching and the development of dermatitis." (PMID 33924978, 2021). "These cells, when activated, release pro-inflammatory cytokines, including IL-4, IL-13, and IL-31 which led to the dermatitis." (PMID 34948125, 2021). "IL-31 is preferentially produced by Th2 cells in Th subsets, and excessive IL-31 production in IL-31 Tg mice resulted in development of dermatitis due to enhancement of type–2 immune responses." (PMID 29703903, 2018). "The degree of skin inflammation assessed by histological analysis was also similar between the wild-type and Il31−/− mice at 24 hours after challenge with FITC or vehicle." (PMID 29703903, 2018). "Previous studies have shown that IL-31 induces pruritus and severe dermatitis, and also regulates other allergic diseases that are characterized by these skin disorders." (PMID 27556734, 2016). "Serum IL-31 levels correlate with disease activity for pruritic skin disorders, and IL-31 seems important in the pathogenesis of allergic asthma as well as ulcerative colitis and Crohn’s disease." (PMID 27809289, 2016). "IL-31 appears to have a suppressive role in models of Th2-induced lung inflammation although evidence also suggests it can induce dermatitis in animal models." (PMID 25849622, 2015). "It acts via a heterodimeric receptor composed of IL-31Rα and oncostatin M receptor β and expression of IL-31 correlates with the expression of IL-4 and IL-13 suggesting that IL-31 is involved in Th2-mediated skin inflammation." (PMID 25756056, 2015).
dermatitis (continued). "A neutralizing anti-IL-31 monoclonal antibody ameliorated scratching behavior in a mouse model of dermatitis." (PMID 22853438, 2012). "Mice treated with intradermal injection of IL-31 or transgenic mice overexpressing IL-31 presented increased scratching behavior and developed severe dermatitis." (PMID 22853438, 2012). "In another study on human skin affected by dermatitis, the addition of staphylococci toxin to the serum of the subject group produced higher IL-31 expression compared to the control group, further proving the role of staphylococci in overexpression of cytokines leading to dermatitis features." (PMID 38500882, 2024). "Although IL-31 activates STAT-3 phosphorylation and enhances C-C motif chemokine 2 (CCL2) secretion in human primary keratinocytes, this phenomenon is not observed in AD keratinocytes with low TLR-2 expression, suggesting a potential link between the functional change of IL-31 and skin inflammation." (PMID 38590314, 2024). "The pathogenesis of dermatitis involves epidermal barriers abnormalities, leading to heterogeneous immunological dysregulations predominantly in type 2 immunity (Th2, IL-4, IL-13, IL-31), but also including varying degrees of upregulation of the Th1 (IFN-γ), Th17 (IL-17), and Th22 axes (IL-22)." (PMID 38550585, 2024). "IL-31 increases scratching and induces severe dermatitis in mice." (PMID 36674561, 2023). "Interleukin-31 (IL-31) induces severe scratching and dermatitis in mice." (PMID 36674561, 2023). "Targeting interleukin-31 aims to decrease pruritus and signs of skin inflammation, which may result in the reduced severity of AD." (PMID 35558086, 2022). "Moreover, continuous or intermittent injections of IL-31 induce scratching and development of dermatitis, whereas the administration of IL-31 antibodies diminishes such behaviors." (PMID 35893400, 2022). "Since these cytokines are involved in skin inflammation, the authors hypothesize that IL-31-specific activation of dendritic cells may be part of a positive-feedback loop of inflammation." (PMID 35742951, 2022). "The blockade of IL31 has been shown to reduce dermatitis in mice and human." (PMID 28147314, 2017). "While IL31 has been shown to contribute to various inflammatory diseases such as dermatitis, inflammatory bowel disease, and airway hypersensitivity, in cancer, its role is still unknown." (PMID 28147314, 2017). "Itching is the major manifestation of AD and other chronic skin disorders, and exacerbated by stimuli that induce sweating, an effect that may be related to the high levels of IL-31 in sweat." (PMID 23874436, 2013). "Our findings suggest that sweat cytokines, notably IL-1 and IL-31, might play roles in the aggravation of some sweat-related skin disorders, such as AD and miliaria rubra, by triggering immune reactions in epidermal keratinocytes." (PMID 23874436, 2013). "Therefore, eosinophils and epidermal keratinocytes responded to IL-31 stimulation and were likely to be involved in the dermatitis and pruritis of transgenic mice overexpressing IL-31." (PMID 22272250, 2012). "IL-31 may enhance skin inflammation through the induction of several chemokine genes such as CCL17, CCL22 and CCL1 in human keratinocytes which subsequently leads to the recruitment of T-cells, and in turn may become new sources of IL-31." (PMID 22853438, 2012). "Therefore, the anti-IL-31 antibody reduced scratching behavior in NC/Nga mice with dermatitis." (PMID 36674561, 2023). "Importantly, intraperitoneal administration of 10 mg/kg anti-IL-31 antibody reduced scratching behavior in NC/Nga mice but did not have any impact on dermatitis, further underlying the importance of IL-31 in AD pruritus." (PMID 25756056, 2015). "IL-31 is also found in eccrine sweat, where it can stimulate keratinocytes to produce the pro-inflammatory cytokine CCL2, further contributing to local skin inflammation." (PMID 41155460, 2025).
dermatitis (continued). "Additionally, IL-31 is activated when the IL-31Rα receptor chain in primary human CD1c+ and monocyte-derived DCs is upregulated by IFN-γ stimulation, leading to a dose-dependent release of inflammatory mediators such as TNF-α, IL-6, CXCL8, CCL2, CCL5, and CCL22, causing skin inflammation." (PMID 38590314, 2024). "This study shows a relationship between IL-31, alloknesis, DRG neuronal IL-31RA expression, neuronal IL-31RA, LLS counts, and dermatitis severity." (PMID 36674561, 2023). "The dermatitis severity and LLS counts induced by mite infestation and IL-31 administration were in the order NC/Nga > BALB/c > C57BL/6." (PMID 36674561, 2023). "We compared the effects of mite infestation or IL-31 administration on the LLS counts and dermatitis scores of NC/Nga, BALB/c, and C57BL/6 mice." (PMID 36674561, 2023). "IL-31 and DRG neuronal IL-31RA are important factors inducing itching and promoting scratching and dermatitis." (PMID 36674561, 2023). "In conclusion, our study offers valuable insights into the multifaceted interactions between IL-31 and CSU, shedding light on the complex role of this cytokine in pruritic skin disorders." (PMID 37762898, 2023). "Ethanol extracts of Ampelopsis brevipedunculata rhizomes inhibited an AD-like skin inflammation through downregulation of serum IgE levels and expression of TNF-α, interferon (IFN)-γ, IL-4, IL-13, and IL-31 in a BALB/c AD model." (PMID 33335525, 2020). "IL-31 is a cytokine produced mainly by activated CD4+ Th2 cells or by mast cells, and is involved in the development of AD-induced skin inflammation and pruritus." (PMID 29910732, 2018). "Here the authors use mice and human samples to show ARNT-independent DOCK8 inhibition of EPAS1 increases transcription of IL-31 in CD4+ T cells, thus driving skin inflammation." (PMID 28067314, 2017). "The correlation between IL-31 mRNA and dermatitis scores (CADESI) was not statistically significant." (PMID 39234173, 2024). "Stimulation with TNF-α/IFN-γ induces the production of pruritic cytokines and chemotactic chemokines in keratinocytes such as TSLP, IL-31, CCL17/TARC, and CCL22/MDC, further expanding skin inflammation with the recruitment of major T cell lineage, Th2 cells, resulting in epidermal damage." (PMID 37958804, 2023). "The expression of TSLP and IL-31 is elevated in the lesional skin of AD patients but not in other dermatitis." (PMID 37239060, 2023). "We also found that treated mice did not exhibit toxic side effects such as dermatitis often found with overexpression of IL31 and there were no changes in body weight during the therapy." (PMID 28147314, 2017). "Although IL-31 has been implicated in pruritus in AD, Dock8−/− OTII Tg mice showed neither skin inflammation nor IgE elevation." (PMID 28067314, 2017). "In the mouse AD model, IL-31 is implicated in skin pruritus as evidenced in the Fluorescein Isothiocyanate (FITC) and Dinitrofluorobenzene (DNFB)-induced contact dermatitis model, though it does not appear to be involved in inducing local skin inflammation." (PMID 38590314, 2024). "Therefore, it might be possible that CD4+ T cells expressing AND TCR are continuously, albeit weakly, stimulated with self-peptide/I-Ab complexes in vivo, and induce skin inflammation by producing IL-31 only when DOCK8 expression is lacking." (PMID 28067314, 2017). "The results showed that mite-infestation and IL-31 administration increased the LLS counts and DRG neuronal IL-31RA mRNA expression and dermatitis scores in the NC/Nga and BALB/c mice but not in the C57BL/6 mice." (PMID 36674561, 2023).